NLRP3 (NLR family pyrin domain containing 3)
Diseases named in the same sentence as NLRP3 in open-access papers (continued):
Sharing a sentence is not in itself a finding about the gene and the disease.
Cerebral ischemia (continued). "NOD-like receptor pyrin domain containing 3 (NLRP3) inflammasome inhibition and autophagy induction attenuate inflammation and improve outcome in rodent models of cerebral ischemia." (PMID 32466385, 2020). "Regarding the regulation of the NLRP3 inflammasome after cerebral ischemia there are different reports depending on the species." (PMID 32645874, 2020). "QDNP significantly decreases cerebral ischemia injury and improve neurological function, protects the neurons against inflammation through a mechanism mediated by NLRP3 signaling." (PMID 32153398, 2020). "In general, cerebral ischemia significantly elevated the expression of NLRP3 inflammasome, which was decreased by treatment with QNDP or QNDP+NLRP3 inhibitor." (PMID 32153398, 2020). "The role of Sirt-1 expression in regulating the activition of the NLRP3 inflammasome induced by cerebral ischemia remains to be established." (PMID 32419986, 2020). "Adiponectin (APN) was found to reduce oxidative stress and NLRP3 inflammasome activation after cerebral ischemia-reperfusion injury by regulating AMPK/GSK-3." (PMID 33574759, 2020). "The NLRP3 inflammasome plays a key role in cerebral ischemia/reperfusion (I/R)-induced inflammatory lesions." (PMID 32419986, 2020). "We focused on NLRP3 inflammasome in the current study to explore the relationship between NF-κB and the NLRP3 inflammasome in cerebral ischemia injury." (PMID 32153398, 2020). "The studies reported that the activation of the NLRP3 inflammasome leads to the development and release of inflammatory cytokines IL-1β and IL-18, suggesting the role for the NLRP3 inflammasome in the initiation and development of cerebral ischemia." (PMID 32153398, 2020). "Other than cerebral ischemia, both NLRP3 inflammation and LPA1 signaling have been independently suggested as promising targets to develop therapeutics in various diseases, including tissue fibrosis and psoriasis." (PMID 33202644, 2020). "In cerebral ischemia/reperfusion injury, the relationship between NLRP3 inflammasome activation and mitophagy has been the most studied." (PMID 33424757, 2020). "Another nutraceutical that has been reported to protect against cerebral ischemia reperfusion in rats by inhibiting NLRP3 is arctigenin." (PMID 32650482, 2020). "This is in accordance with previous studies, in which knock-down of Nrf2 led to NLRP3 activation in cerebral ischemia-reperfusion injury." (PMID 31311094, 2019). "An over accumulation of free radicals induced by cerebral ischemia-reperfusion injury can activate the NLRP3 inflammasome." (PMID 31747940, 2019). "The present research was the first preclinical study to examine the regulatory effect of QKL injection on AMPK/NLRP3 inflammasome pathway activation following cerebral ischemia-reperfusion injury." (PMID 31747940, 2019). "The NOD-like receptor pyrin 3 (NLRP3) inflammasome is activated in cerebral ischemia and thus, is an effective therapeutic target." (PMID 31747940, 2019). "Our study demonstrated the meisoindigo had neuroprotective effects on cerebral ischemia through decreasing NLRP3 inflammasome components expression via inhibition of activation of the TLR4/NF-κB pathways." (PMID 31920554, 2019). "NLRP3 inflammasome is one of the best characterized inflammasomes to date, and is the most strongly relevant in cerebral ischemia." (PMID 31747940, 2019). "Future studies should seek to identify the potential ingredients in the QKL injection that target the AMPK/NLRP3 inflammasome signal pathway in the treatment of cerebral ischemia." (PMID 31747940, 2019). "Nrf2 prevents NLRP3 inflammasome activation by regulating Trx1/TXNIP complex in cerebral ischemia-reperfusion injury." (PMID 31920652, 2019). "Our results revealed that KD and BHB were able to improve cerebral ischemia by inhibiting NLRP3 inflammasome activation, which was ascribed to the suppression of Drp1-mediated mitochondrial fission and the inhibition of ER stress." (PMID 29662437, 2018).
Cerebral ischemia (continued). "Concerning NLRP3 inflammasomes, a knockdown of Nrf2 expression enhanced NLRP3 inflammasome activity in a model of cerebral ischemia reperfusion injury and in brain injury after intracerebral hemorrhage." (PMID 29438305, 2018). "The activation of TLR-4 activates NF-κB during cerebral ischemia, and NF-κB further promotes the production of NLRP3 and IL-1β— thus, enhancing inflammation." (PMID 30618576, 2018). "We aim to investigate the effect and the potential mechanism of NLRP3 inflammasome in diabetic mice with cerebral ischemia-reperfusion injury." (PMID 29853850, 2018). "To provide evidence of MCC950 to the protective effect of cerebral ischemia reperfusion in diabetic mice, we measured the mRNA levels of NLRP3, IL-1β, and caspase-1 in the boundary zone adjacent to the ischemic core." (PMID 29853850, 2018). "When compared with the vehicle group, MCC950, the NLRP3 inhibitor significantly reduced the neurological deficit score 24 hr after cerebral ischemia reperfusion in diabetic mice (2.545 ± 0.963 versus 3.065 ± 0.629, P < 0.05, n = 22 and 31)." (PMID 29853850, 2018). "Recent studies have demonstrated that in response to cerebral ischemia, NLRP3 inflammasomes promote inflammatory responses in neurons and glial cells, resulting in tissue damage." (PMID 30618576, 2018). "Our study showed that the inhibition of NLRP3 inflammasome by MCC950 ameliorates cerebral ischemia-reperfusion injury in diabetic mice." (PMID 29853850, 2018). "In support of this possibility, NLRP3 knockout mice have been shown to have significantly reduced infarct size after FCI, suggesting that NLRP3 inflammasome activation contributes to neuronal damage and cell death after cerebral ischemia." (PMID 27843532, 2016). "Of all of the inflammasome proteins, NLRP3 is by far the most studied inflammasome in cerebral ischemia studies." (PMID 27843532, 2016). "In macrophages and in animal models, studies have also defined a role for the NLRP3 inflammasome in the initiation and development of cerebral and myocardial ischemic diseases, including cerebral ischemia/stroke and myocardial ischemia." (PMID 26594174, 2015). "Some studies have shown that when the NLRP3 inflammasome is activated, it releases downstream pro-inflammatory mediators such as IL-1β and IL-18, which become one of the key factors triggering neuroinflammation after cerebral ischemia–reperfusion." (PMID 39926015, 2025). "Although acupuncture has been demonstrated to exert neuroprotective effects in cerebral ischemia, its effects on mitophagy and interactions with NLRP3 inflammasomes remain unknown." (PMID 40260133, 2025). "The results indicate that calycosin might offer protection against brain ischemia-reperfusion damage by blocking the HMGB1/NLRP3-driven pyroptosis mechanism in HAPI microglial cells." (PMID 40606597, 2025). "By contrast, the inhibition of NLRP3 inflammasome activity suppresses microglial activation and M1 polarization, thereby downregulating the inflammatory response in the penumbra and reducing the infarct size in the early stages of cerebral ischemia." (PMID 39391701, 2024). "The NLRP3 inflammasome, a critical component in the innate immune system, participates the progression of microglial polarization in the ischemic area in the acute stage of cerebral ischemia." (PMID 39391701, 2024). "Additionally, some studies revealed that pharmacological inhibition of NLRP3 inflammasome-mediated inflammatory response displayed strong neuroprotective effects against transient focal cerebral ischemia injury in mice and rats." (PMID 38667787, 2024). "When specifically inhibiting the CKLF1/CCR4 axis, the activation of NLRP3 and the subsequent inflammatory response process could be further inhibited, thus protecting neurological function and improving cerebral ischemia." (PMID 38773776, 2024). "Considering the involvement of NLRP3 in cerebral ischemia-reperfusion damage, the effect of AS-IV could explain why AS-IV+HSYA was effective." (PMID 39199474, 2024).
Cerebral ischemia (continued). "This combination may alleviate cerebral ischemia-reperfusion injury in rats by downregulating the signaling molecules of the NF-κB/NLRP3/Caspase-1/GSDMD pathway." (PMID 39199474, 2024). "Mitophagy inhibits the activation of the NLRP3 inflammasome in cerebral ischemia." (PMID 38895624, 2024). "The effect of JDHXD promoting autophagy to clear NLRP3 to inhibit pyroptosis on cerebral ischemia-reperfusion inflammatory injury is currently unknown." (PMID 39139639, 2024). "Inhibition of NLRP3 inflammasome expression can simultaneously inhibit the expression of downstream pyroptosis pathway-related proteins, limit the inflammatory response and alleviate cerebral ischemia-reperfusion injury." (PMID 38601463, 2024). "In summary, our study provides novel evidence that ChemR23 signaling could ameliorate brain injury via inhibiting NLRP3 inflammasome-mediated pyroptosis in cerebral ischemia." (PMID 38178174, 2024). "The assembly of the inflammasome is also a key part of the pyroptotic pathway during cerebral ischemia, and the upregulation of the NLRP3 inflammasome complex, as well as IL-1β and IL-18, has been demonstrated in the brain tissue of patients with cerebral ischemia." (PMID 37373274, 2023). "Thus, TLR4/MyD88/NF-κB signaling pathway exerts vital importance on regulating NLRP3 activation, neuronal pyroptosis and microglia activation after cerebral ischemia." (PMID 38273974, 2023). "It was reported that NLRP3/caspase-1-dependent pyroptosis participated in the cerebral ischemia/reperfusion injury and cognitive decline after focal cortical infarction, NLRP3 inhibitor and caspase-1 inhibitor could improve the symptoms, respectively." (PMID 37332874, 2023). "Additionally, a recent study reported that hypoxic preconditioning (HPC) suppressed NLRP3 inflammasome activation and prevented cerebral ischemia/reperfusion injury in an ischemic brain." (PMID 37371374, 2023). "This study demonstrated that downregulated XBP-1 could inhibit pyroptosis by inhibiting the NLRP3/Caspase-1/GSDMD pathway in the hippocampus which rescues cerebral ischemia/reperfusion injury." (PMID 35497095, 2022). "Besides, the involvement of NLRP3 inflammasome has also been confirmed in the effects of Ruscogenin on cerebral ischemia-induced dysfunction of blood-brain barrier." (PMID 35800007, 2022). "Herbal drugs that target NLRP3 inflammasome after cerebral ischemia–reperfusion (I/R) injury." (PMID 35600078, 2022). "Additionally, they reduce cerebral ischemia–reperfusion injury by promoting microglial polarization from M1 to M2, thereby inhibiting the expression of proteins such as NLRP3 and GSDMD." (PMID 36292924, 2022). "Therefore, the NLRP3 inflammasome is likely to induce the inflammatory response of cerebral ischemia–reperfusion injury through microglia." (PMID 36818726, 2022). "NLRP3, as the initiating factor of aseptic inflammatory response of the central nervous system after cerebral ischemia, induces cell pyroptosis, resulting in nerve cell injury, and plays a key role in the inflammatory cascade effect after cerebral ischemia/reperfusion." (PMID 35600074, 2022). "Studies have found increased NLRP3 inflammasome expression in brain tissue after cerebral ischemia." (PMID 36013423, 2022). "However, additional studies are required to fully understand how NLRP3 functions through monocytes in cerebral ischemia." (PMID 36818726, 2022). "Nod-like receptor, pyrin containing 3 (NLRP3)-inflammasome is a member of innate cell sensors, which can produce a variety of proinflammatory cytokines and mediate nerve cell dysfunction, thus leading to cell death after cerebral ischemia." (PMID 36091745, 2022). "Our subsequent results also confirmed that iTBS could down-regulate the high level of TLR4, NLRP3, and phosphorylation of NFκB induced by cerebral ischemia." (PMID 35690810, 2022). "Nrf2 and NLRP3 play a role in cerebral ischemia–reperfusion injury at the same time." (PMID 36818726, 2022).
Cerebral ischemia (continued). "In addition, a very recent study also determined that Tet attenuated cerebral ischemia/reperfusion injury by inhibiting NLRP3 via Sirt-1, which silenced many key genes involved in this NLRP3 pathway." (PMID 34417574, 2022). "Melatonin via suppressing ROS-induced NLRP3 activation after cerebral ischemia could ameliorate HT in hyperglycemic rats." (PMID 36238294, 2022). "NLRP3 inflammasome activation may trigger or exacerbate neuroinflammation, thereby promoting cerebral ischemia injury." (PMID 33735403, 2021). "Several studies have highlighted the neuroprotective effect of minocycline, a tetracycline antibiotic, in focal cerebral ischemia injury animal models, showing that early treatment or pretreatment prevents the activation of microglia and attenuates NLRP3 inflammasome signaling." (PMID 33572080, 2021). "The compound IMM-H004, a new coumarin derivative, downregulated the amount of CKLF1 binding with C–C chemokine receptor type 4, further suppressing the activation of the NLRP3 inflammasome and the following inflammatory response, thereby improving brain ischemia-reperfusion injury." (PMID 35008558, 2021). "For example, in a mouse model of focal cerebral ischemia-reperfusion injury, NLRP3 inflammasome inactivation was mediated by inhibition of the TLR4/NF-κB signaling pathway, which resulted in HMGB1 downregulation, consequently alleviating brain damage in ischemic stroke." (PMID 33384585, 2020). "In addition, we found that not all NeuN-immunoreactive neurons in the brain slices expressed NLRP3 after cerebral ischemia, which is worth exploring in depth." (PMID 32153398, 2020). "Moreover, in a mouse model of global cerebral ischemia, the NLRP3/ASC/caspase-1 signaling pathway was involved in ischemic brain injury." (PMID 33384585, 2020). "Studies have also found that activating Parkin-dependent mitophagy could inhibit the activation of NLRP3 inflammasome to reduce cerebral ischemia/reperfusion injury." (PMID 33424757, 2020). "Inhibition of the NLRP3 inflammasome activation may have a neuroprotective role after cerebral ischemia." (PMID 33384585, 2020). "In our present study, QNDP could reduce the expression of NLRP3, cleaved caspase-1, IL-1β, and IL-18, alleviate brain edema, and improve the neurological function after cerebral ischemia." (PMID 32153398, 2020). "Thus, it is necessary and meaningful to identify a drug that can control NLRP3 inflammasome activation in cerebral ischemia." (PMID 32153398, 2020). "Therefore, the aim of this study was to investigate the possible effects of Tet on cerebral ischemia and the related mechanisms involved in NLRP3 inflammasome." (PMID 32419986, 2020). "Therefore, the AMPK/NLRP3 inflammasome pathway has the potential to be a therapeutic target in the treatment of cerebral ischemia." (PMID 31747940, 2019). "In conclusion, our study indicated that when diabetic mice suffered from cerebral ischemia-reperfusion injury, it may be related to the sustained activation of NLRP3 inflammasome." (PMID 29853850, 2018). "A similar multicell induction of NLRP3 pathway factors has been reported previously in the cerebral cortex after focal cerebral ischemia or traumatic brain injury, demonstrating that NLPR3 factors are expressed in neurons, astrocytes, and microglia after brain injury." (PMID 27843532, 2016). "Moreover, various drug studies have reported that the aggravation of the upstream NLRP3 inflammasome signaling pathway and IL-1β may serve as a neuroprotective potential for cerebral ischemia and CSVD." (PMID 36676165, 2023).
Cerebral ischemia (continued). "However, reports have also shown that the inhibition of NLRP3 inflammasome-mediated pyroptosis may possess neuroprotective benefits following cerebral ischemia and potentially halting the progression of CSVD." (PMID 36676165, 2023). "HGWD may alleviate cerebral ischemia injury via Sirt1/NF-κB/NLRP3 inflammatory signaling pathway." (PMID 37650573, 2023). "Electroacupuncture (EA) can reduce neuronal injury caused by cerebral ischemia–reperfusion, and we speculated that EA can prevent neuronal pyroptosis after cerebral ischemia–reperfusion by regulating the nucleotide-binding oligomerization domain-like receptor protein 3 (NLRP3)/caspase-1 pathway." (PMID 35600074, 2022). "This treatment reduced the expression of NLRP3, caspase-1, and IL-1β, and the occurrence of cell pyroptosis and inflammatory response, suggesting that the protective effect of EA on cerebral ischemia/reperfusion injury may be played by inhibiting the pyroptosis pathway dependent on caspase-1." (PMID 35600074, 2022). "The miRNA-20b/NLRP3 axis may be a putative therapeutic target for cerebral ischemia." (PMID 36275741, 2022). "To further investigate whether MFSCE attenuates neuroinflammation after cerebral ischemia, we determined the expression of NLRP inflammasome-associated proteins, including NLRP1, NLRP3, ASC, CL-caspase-1, CL-caspase-11, IL-1β, and IL-18 in the ischemic cortex using Western blotting." (PMID 35454994, 2022). "However, the expression of NLRP3 in neurons after cerebral ischemia is probably chronological." (PMID 32625078, 2020). "Furthermore, diazoxide could reduce NLRP3 activation during cerebral ischemia/reperfusion injury through protecting mitochondria." (PMID 33328988, 2020). "In addition, NLRP3 knockdown by siRNA effectively ameliorated cerebral ischemia damage." (PMID 32419986, 2020). "Therefore, we want to assess whether mitophagy induction could alleviate cerebral ischemia-reperfusion injury by eliminating dysfunctional mitochondria and inhibiting NLRP3 inflammasome activation." (PMID 31416289, 2019). "Furthermore, it has been recently observed that mitophagy may exert a neuroprotective effect during cerebral ischemia-reperfusion injury and it can negatively regulate NLRP3 inflammasome activation." (PMID 31416289, 2019). "Furthermore, we found that the mRNA transcription levels of NLRP3, IL-1β, and caspase-1 in the core ischemic area were remarkably amplified in diabetic mice with cerebral ischemia-reperfusion injury, whereas this phenomenon was obviously attenuated by MCC950 pretreatment." (PMID 29853850, 2018). "In studies of DCM, autoimmune prostatitis, cerebral ischemia, and other diseases, modulation of the PI3K/AKT pathway has been shown to inhibit NLRP3 activation and regulate downstream inflammatory factor expression." (PMID 40430076, 2025). "In the Western blot and immunofluorescence analyses, the expression levels of pyroptosis-related factors, such as NF-κB, NLRP3, GSDMD, ASC, Caspase-1, and IL-1β, were increased significantly after cerebral ischemia-reperfusion injury." (PMID 39199474, 2024). "Inhibition of the NLRP3 inflammasome by GAS has been demonstrated in vivo and in vitro using animal models of myocardial ischemia, cerebral ischemia, fulminant hepatitis, traumatic brain injury, septic shock, and cognitive dysfunction." (PMID 38835032, 2024). "Moreover, previous studies have also reported that, following CSVD or cerebral ischemia, the NLRP3 inflammasome could possibly be activated in microglia cells through the activation of a purinergic signaling cascade by P2X7R and TLRs that recognize PAMPs and DAMPs." (PMID 36676165, 2023). "Collectively, in cerebral ischemia/reperfusion injury, LCN2 binds to 24p3R on the astrocyte membrane and facilitates NLRP3 activation, which ultimately triggers astrocyte pyroptosis and pro-inflammatory effects." (PMID 37353794, 2023).